LEP (leptin)
Diseases named in the same sentence as LEP in open-access papers (continued):
Sharing a sentence is not in itself a finding about the gene and the disease.
breast cancer (continued). "Women with increased levels of serum leptin often have a higher incidence of breast cancer than women with normal leptin levels." (PMID 27588409, 2016). "Mechanistically, we discovered that activated FXR counteracts leptin action on breast cancer cells through its ability to induce the expression of the suppressor of cytokine signaling 3 (SOCS3), a prototype molecule of the SOCS family." (PMID 26899873, 2016). "In fact, estrogenic stimulation promotes breast cancer pathogenesis and tumorgenesis, while insulin and leptin exhibit proliferative, mitogenic, and anti-apoptotic activities in mammary cells, thus promoting tumor growth." (PMID 27464488, 2016). "GW4064 inhibited growth, motility and invasiveness induced by leptin as well as by CAF-conditioned media in different breast cancer cell lines." (PMID 26899873, 2016). "We have previously shown that this peptide inhibits leptin-induced breast cancer growth in vitro and exhibits anti-neoplastic activities in vivo." (PMID 26556856, 2016). "Our previous study has shown that leptin stimulates IL-8 expression via activating the PI3K/AKT signaling pathway in breast cancer cells MCF7 and SKBR3." (PMID 27588409, 2016). "When activated by leptin or estrogen in breast cancer cells, STAT5 requires c-Src and epidermal growth factor (EGF)." (PMID 27472371, 2016). "Moreover, we recently demonstrated that leptin is also secreted by a subpopulation of fibroblasts, known as cancer-associated fibroblasts (CAFs), within the tumor microenvironment, and that CAFs-secreted leptin promotes proliferation, migration, and invasiveness of breast cancer cells." (PMID 26899873, 2016). "In conclusion, Sam68 seems to participate in both leptin and insulin receptor signalling in human breast cancer cells, mediating the trophic effects of these hormones in proliferation and cellular growth." (PMID 27415018, 2016). "SOCS3 has been identified as an inducible suppressor of leptin signaling, and in breast cancer cells, its overexpression has been shown to decrease proliferation and anchorage-independent growth." (PMID 26899873, 2016). "Studies in cell lines derived from breast cancer have shown that malignant epithelial cells, also induces expression functional of CP450Arom through leptin and its receptor." (PMID 26877711, 2016). "Biological effects of leptin and insulin in promoting growth and proliferation have been extensively reported in many different cell systems, including breast cancer cells." (PMID 27415018, 2016). "The stimulatory effect of leptin on the proliferation of different breast cancer cells, T47-D, MCF7 and Zr-75-1 has also been examined." (PMID 27480179, 2016). "Conditioned media (CM) from cancer-associated fibroblasts and breast adipocytes significantly increased mammosphere formation in breast cancer cells and depletion of leptin from CM completely abrogated this effect." (PMID 26556856, 2016). "The results demonstrated that leptin promoted breast cancer cells EMT, visibly activated the PI3K/AKT signaling pathway, and upregulated PKM2 expression." (PMID 27769315, 2016). "Synergy of leptin/STAT3 with HER2 receptor induces tamoxifen resistance in breast cancer cells through regulation of apoptosis-related genes." (PMID 27472371, 2016). "We then examined the ability of the FXR ligand to affect leptin-induced breast cancer cell movement in wound-healing scratch assays." (PMID 26899873, 2016). "Leptin and insulin have previously been demonstrated to activate these pathways in cancer and, specifically, breast cancer cells." (PMID 27415018, 2016). "Now, we have shown that Sam68 plays a role in leptin and insulin signal transduction pathways in three different adenocarcinoma breast cancer cell lines." (PMID 27415018, 2016). "We have previously demonstrated that the HSP90, a main functional component of this chaperone complex, is a target of leptin in breast cancer cells." (PMID 26556856, 2016).
breast cancer (continued). "Leptin, a key adipokine secreted from adipocytes, shapes the tumor microenvironment, potentiates the migration of breast cancer cells and angiogenesis, and is also involved in EMT." (PMID 27769315, 2016). "Two clinical reports fail to link circulating leptin with breast cancer recurrence, although another has shown leptin to be associated with distant recurrence and death even when statistical models were adjusted for BMI and body weight." (PMID 27338371, 2016). "Leptin upregulation of VEGF/VEGFR-2 is mediated by leptin-induced JAK/STAT3-Notch expression while also showing that leptin regulation of VEGF/VEGFR2 in breast cancer involves the activation of Src and Gbr2/Gab2/STAT3, suggesting crosstalk with Rho-GTPases." (PMID 27472371, 2016). "Leptin has been shown to stimulate proliferation of breast cancer cell lines in vitro, to stimulate tumor growth in nude mice via activation of the extracellular signal-related kinase (ERK), and to stimulate growth of carcinogen-induced rat tumors." (PMID 27338371, 2016). "This study found that leptin didn’t only induce breast cancer cells EMT, but also upregulated PKM2 expression, which resulted from the activation of PI3K/AKT pathway." (PMID 27769315, 2016). "Previous studies indicate that leptin, one of the adipokines secreted from adipocytes, is an important factor that links obesity with breast cancer." (PMID 27769315, 2016). "The role of leptin in the regulation of BCSC activity was then evaluated by using patient-derived breast cancer cells isolated from metastatic ascites or pleural effusions." (PMID 26556856, 2016). "Serum leptin has been studied in breast cancer patients and concentrations were higher in women with high-grade tumors." (PMID 27050378, 2016). "We have confirmed the growth promoting effect of insulin and leptin in breast cancer cells, as well as the importance of Sam68 expression to exert this effect, since down-regulation of Sam68 impairs the proliferative action of both hormones." (PMID 27415018, 2016). "Scratch and transwell chamber assay showed that both recombinant IL-8 and leptin-induced M2 macrophage-derived IL-8 promoted the migration and invasion of human breast cancer cells MCF7 and MDA-MB-231 (All P < 0.01)." (PMID 27588409, 2016). "Particularly, we demonstrated that the specific FXR ligand, GW4064, affects the signaling of the adipokine leptin that we have recently identified as one of the most important molecules involved in the tumor-promoting activity of CAFs in breast cancer cells." (PMID 26899873, 2016). "Co-culture of adipocytes and breast cancer cells resulted in a doubling of the leptin levels compared to adipocytes cultured alone whereas the levels were tripled in presence of estradiol." (PMID 27059487, 2016). "Next, we investigated the efficacy of HNK to block leptin-induced invasion and migration of breast cancer cells using Matrigel invasion and spheroid migration assay." (PMID 26036628, 2015). "The data suggest that obASC-derived leptin enhances several central processes such as proliferation and metastasis of cancer cells that ultimately enhance the aggressiveness of breast cancer cells." (PMID 26286584, 2015). "Treatment of breast cancer cells with leptin exhibited striking increase in MTA1, Wnt1, β-catenin and cyclin D1 expression in comparison to untreated cells." (PMID 26036628, 2015). "The current study investigates the impact of inhibiting leptin expression in lnASCs and obASCs on breast cancer cell (BCC) growth and progression." (PMID 26286584, 2015). "Women who are obese at the time of breast cancer diagnosis have higher overall mortality than normal weight women and some evidence implicates adiponectin and leptin as contributing to prognostic disadvantage." (PMID 26132992, 2015). "For example, breast cancer cells have been shown to be capable of producing leptin to, in turn, impact on stromal cells and tumor-infiltrating macrophages." (PMID 26120967, 2015).
breast cancer (continued). "We have reported the existence of a crosstalk between oncogenic signaling pathways in breast tumor cells in humans and mice triggered by leptin, IL-1 and Notch (NILCO) critical to leptin-induced breast cancer promotion." (PMID 25599228, 2015). "We found that HNK effectively inhibits leptin-induced EMT of breast cancer cells as evident from morphological changes and molecular alterations of mesenchymal and epithelial genes." (PMID 26359358, 2015). "Breast cancer cells exhibited augmentation of invasion and migration potential upon leptin treatment which was effectively inhibited with HNK treatment." (PMID 26036628, 2015). "Significant migration of MCF7, MDA-MB-468, MDA-MB-231, SUM149, SUM159 and T47D breast cancer cells observed in the presence of leptin was inhibited in the presence of HNK treatment." (PMID 26359358, 2015). "Studies have shown that expression of leptin and its receptor is significantly increased in primary breast cancer with metastases." (PMID 26199932, 2015). "Leptin promotes breast cancer progression through the activation of mitogenic, antiapoptotic, and metastatic pathways." (PMID 26251693, 2015). "Together, these results show that HNK treatment results in effective inhibition of leptin-induced epithelial-mesenchymal transition, mammosphere formation, stemness and migration of breast cancer cells." (PMID 26359358, 2015). "To assess the clinical utility of our leptin antagonist against human breast cancer progression, we tested LDFI effects in SKBR3 xenografts implanted in female nude mice." (PMID 25721149, 2015). "Because computation of the ratio of adiponectin to leptin has been suggested as an index for assessing net effects of these adipokines on diseases like breast cancer, the ratio was also evaluated." (PMID 26132992, 2015). "Recently, it has been found that leptin contributes to the maintenance of cancer stem-like cells in breast cancer cells." (PMID 26053184, 2015). "Focus on the adipokine leptin, which has been shown to have a central role in breast cancer pathogenesis, indicated it modulates macrophage phenotypes and functions." (PMID 25599228, 2015). "In the present study, we investigated the role of autophagy in leptin-induced cancer cell proliferation using human hepatoma (HepG2) and breast cancer cells (MCF-7), and tumor growth in a xenograft model." (PMID 25704884, 2015). "Breast cancer cells treated with leptin and honokiol were examined for the expression of Cyclin D1 as a functional control." (PMID 26359358, 2015). "RT-PCR analysis showed that the levels of the Ob gene increased by leptin were strongly reduced in the presence of the peptide in both breast cancer cells." (PMID 25721149, 2015). "As we previously discussed, leptin’s concentration in the in vitro-simulated murine obese mammary tumor microenvironment is decreased after adipocytes crosstalk with E0771 tumor cells (which do not produce leptin themselves) and with macrophages." (PMID 25599228, 2015). "Involvement of inflammation, in addition to adipokines and obesity in breast cancer seem to be a convincing theory, since a huge interest has been developed in the current years in studying the function of leptin and adiponectin in mammary tumor growth." (PMID 26431176, 2015). "We previously show that leptin induces canonical activation of Wnt1 signaling through β-catenin-dependent mechanisms in breast cancer cells." (PMID 26036628, 2015). "Leptin secretion from adipose tissue is believed to promote breast cancer directly and independently and also through its effects on estrogen and insulin signaling pathways." (PMID 26251693, 2015). "The proinflammatory cytokines and chemokines secreted by macrophages and adipose cells, including TNF-α, IL-6, MCP-1 and leptin, can directly stimulate breast cancer cell proliferation and invasion." (PMID 26132316, 2015).
breast cancer (continued). "Leptin also plays a central role in the acquisition of mesenchymal characteristics by inducing breast cancer cells to undergo a transition from epithelial to spindle-like mesenchymal morphology." (PMID 26359358, 2015). "Our results identified that there were statically higher serum levels of leptin, visfatin, and resistin and lower serum level of adiponectin in breast cancer patients compared to healthy controls." (PMID 25838618, 2015). "Utilizing mammosphere assay that relies on the unique property of breast cancer cells with stem-like potential to form large, round, unattached floating spheroid colonies (termed mammosphere), we showed that leptin induced mammosphere formation." (PMID 26359358, 2015). "The mechanism(s) by which ASC-derived leptin affects BCC signaling pathways was investigated using a custom breast cancer PCR array to determine changes in the expression of previously identified cell cycle, apoptotic, and angiogenic genes." (PMID 26286584, 2015). "Developing novel strategies to block specific biologic mechanism(s) by which leptin contributes to breast cancer progression and prognosis is essential for individualizing care for improving outcomes among obese breast cancer patients." (PMID 26036628, 2015). "The role of leptin produced by obASCs on breast cancer cells (BCCs) was investigated in this study by inhibiting the expression of leptin using a short hairpin RNA (shRNA) knockdown strategy." (PMID 26286584, 2015). "We first examined the effect of HNK on leptin-induced cell-viability, clonogenic potential and anchorage-independent growth of breast cancer cells." (PMID 26036628, 2015). "Our results show that HNK significantly inhibits leptin-induced breast-cancer cell-growth, invasion, migration and leptin-induced breast-tumor-xenograft growth." (PMID 26036628, 2015). "Chromatin immunoprecipitation analysis revealed that breast cancer cells treated with leptin and IL-6 (used as a positive control) showed increased recruitment of Stat3 at the miR-34a promoter while HNK treated cells showed decreased Stat3 recruitment." (PMID 26036628, 2015). "The present study suggests that hepatic and breast cancer can be highly developed in the obese due to leptin-induced autophagic process." (PMID 25704884, 2015). "Similar to reports in breast cancer cells, we observed leptin-induced expression of EMT genes and stemness markers in CICs isolated from ovarian cancer (CD44+), supporting its role in the maintenance of a more aggressive phenotype." (PMID 26053184, 2015). "Our previous studies have put forth Stat3 activation as an integral event in leptin signaling mediating oncogenic actions of leptin in breast cancer." (PMID 26036628, 2015). "We recently presented a pivotal role of leptin in acquisition of mesenchymal characteristics and aggressive behavior in breast cancer cells." (PMID 26359358, 2015). "In conclusion, the present study has demonstrated that leptin induces autophagy in hepatic and breast cancer cells, which in turn leads to the suppression of apoptosis." (PMID 25704884, 2015). "To this end, we assessed the expression of Oct4, and Nanog in leptin-treated breast cancer cells and found that the expression of pluripotency genes was higher in leptin-treated cells with respect to the expression in untreated cells." (PMID 26359358, 2015). "If weight loss is shown to favorably affect survival prognosis among breast cancer patients, CHOICE findings fail to provide strong support for investigating a causal linkage between adiponectin or leptin and changes in prognosis mediated by weight loss." (PMID 26132992, 2015). "Interestingly, we demonstrated the ability of the peptide LDFI to reverse the leptin-mediated up-regulation of its own gene expression underlying how this peptide negatively interferes in the short autocrine loop maintained by leptin on Ob gene in breast cancer cells." (PMID 25721149, 2015).
breast cancer (continued). "Present data further confirm previous findings showing that TNBC cells in culture (MDA-MB231) secreted more leptin (approximately four-fold) than ER+ breast cancer cells (MCF-7)." (PMID 24716804, 2014). "It is known that inhibition of Notch and leptin signaling can revert the transformed phenotype of human breast cancer cell lines." (PMID 24716804, 2014). "Leptin affects several intracellular messengers that regulate proliferation and survival of breast cancer cells." (PMID 25338520, 2014). "All these observations confirm that leptin can act not only by endocrine and (or) paracrine action on mammary tumor cells, but also via an autocrine pathway." (PMID 25866478, 2014). "Previous in vitro studies have demonstrated that leptin induces cell proliferation in a variety of breast cancer cell types, within physiological concentrations (25–100 ng/ml)." (PMID 24959279, 2014). "ER+ patients showed significantly higher BMI and leptin levels in comparison with that of ER− breast cancer patients." (PMID 25338520, 2014). "The current work, however, aimed to direct inhibition of leptin expression and secretion in human T47D breast cancer cell line using curcumin." (PMID 25866478, 2014). "Recently, we showed for the first time ObR RNA expression and leptin secretion in CAFs, proposing a novel integral role for leptin in mediating the bidirectional crosstalk between breast cancer cells and CAFs driving tumor growth and invasion." (PMID 25505738, 2014). "In the present study, SK-BR-3 and MDA-MB-231 breast cancer cell lines were treated with various concentrations (6.25–1,600 ng/ml) of recombinant leptin and changes in cell proliferation were assessed." (PMID 24959279, 2014). "Second, adipose tissue produces two adipokines (cytokine-like factors), leptin and adiponectin, that affect breast cancer biology." (PMID 25653879, 2014). "Positive detection of leptin within breast cancer tissues significantly correlated to higher levels of IL-1R tI, VEGF, and, OB-R." (PMID 24716804, 2014). "Leptin stimulates angiogenesis and breast cancer invasiveness through the enhanced neovascularization, so it is a key factor to control breast cancer progression." (PMID 25147760, 2014). "In breast cancer leptin is also a positive regulator of vascular endothelial growth factor (VEGF) and blockade of leptin signalling markedly reduces VEGF expression and the tumour growth in mouse xenografts." (PMID 25482303, 2014). "In this regard, we recently identified leptin as a main regulator in the crosstalk between breast cancer cells and CAFs, adding, for the first time, leptin to the list of growth factors able to mediate tumor–stromal interaction." (PMID 25505738, 2014). "In the last decades, a plethora of data, strongly support the idea that leptin activity is correlated with breast cancer occurrence." (PMID 25505738, 2014). "Leptin is one of the prominent adipokines and its intratumoural levels are positively correlated with poor breast cancer prognosis, advanced stage, metastasis and recurrence." (PMID 25482303, 2014). "The abrogation of leptin signaling impaired the growth of tumors and expression of angiogenic biomarkers in human breast cancer xenografts, and in mouse carcinogenic-induced and syngeneic mammary tumors, which was more evident in obese contexts." (PMID 24716804, 2014). "In MDA-MB-231 breast cancer cells, leptin induced a robust concentration-dependent increase in proliferation in two independent studies." (PMID 24959279, 2014). "Leptin stimulates human breast cancer cell lines, whereas adiponectin acts protectively, inhibiting the growth of these cell lines." (PMID 25653879, 2014). "Reactive oxygen species levels were positively correlated with BMI, leptin and IL-6 in ER+ breast cancer patients." (PMID 25338520, 2014). "The highest leptin concentration used in vitro to examine changes in T47D breast cancer cell proliferation was 1,000 ng/ml." (PMID 24959279, 2014).